REN (renin)
Diseases named in the same sentence as REN in open-access papers (continued):
Sharing a sentence is not in itself a finding about the gene and the disease.
Hypertension (continued). "The primary goal of this review article was to determine whether the three RAAS-associated SNPs, Renin-rs16853055, AGT-rs3789678 and ACE-rs4305 are genetically linked to the development of hypertension in preeclampsia." (PMID 38411777, 2024). "This activates renin-mediated hypertension initially, and with repeated injury, ischemia-mediated hypertension, which may have implications in preeclampsia development." (PMID 39100275, 2024). "cGMP is formed in response to NO and natriuretic peptides, including the atrial natriuretic factor ANF (NPPA) (BN) and the brain natriuretic factor ANFB (NPPB) (BN), and has been shown to modulate hypertension via different mechanisms, as vasorelaxation or renin reduction." (PMID 38326862, 2024). "The renin–angiotensin–aldosterone system (RAAS) is a key hormonal system affecting hypertension." (PMID 39479630, 2024). "Interestingly, there is also an indirect relationship between the kidney and hypertension via renin, a component of the renin–angiotensin system (RAS), which is currently considered the cutting-edge factor in hypertension." (PMID 39513878, 2024). "By affecting SMAD7, vascular endothelial growth factor, renin pathways, and subclinical inflammation, microRNA-21 is involved in the development and progression of hypertension and HMOD, including left ventricular hypertrophy and arterial damage measured by the cIMT and PWV." (PMID 39598074, 2024). "Thus, renin-independent aldosterone production can be detected in individuals with normotension, mild hypertension, as well as, RH, with corresponding superior effectiveness of MRA therapy." (PMID 39445045, 2024). "Like licorice toxicity, AME results in low-renin hypertension with suppressed aldosterone levels." (PMID 39498427, 2024). "The precise mechanism behind the development of hypertension after COVID-19 remains unclear, but it is suggested that endothelial injury and dysfunction of the renin–angiotensin–aldosterone system may be contributory." (PMID 38339115, 2024). "Normalization of insulin secretion, primarily through dietary correction, as well as pharmacotherapy that restores the functional balance of insulin and renin-angiotensin signaling systems seem essential for the prevention and treatment of IR, hypertension and diabetic complications." (PMID 38323106, 2024). "In addition, the over-activation of the renin-angiotensin-aldosterone system (RAAS) is also considered to be an important factor behind the progression of hypertension and HICH." (PMID 39697438, 2024). "There may be multiple aetiologies and triggers for hypertension in post-menopausal females, with renin-angiotensin-aldosterone system dysregulation, sympathetic activation and declining oestrogen levels being key factors." (PMID 38861130, 2024). "Approximately 70% of patients with hypertension have elevated level of renin." (PMID 38632457, 2024). "Similar to the other comorbidities present in the pediatric MetS, the therapeutic market targeting arterial hypertension is constantly developing, the newest products coming into focus being endothelin receptor antagonists (Darusentan) and renin inhibitors (Aliskiren)." (PMID 39723164, 2024). "It is well known that angiotensin II plays an important role in the development of hypertension, so the involvement of the renin-angiotensin-aldosterone system may also explain, to some extent, the pathophysiology of these two diseases." (PMID 38800482, 2024). "One mechanism suggests that hyperinsulinemia closely related to IR may activate the renin-angiotensin-aldosterone system, promote renal sodium retention and ultimately lead to hypertension." (PMID 38664804, 2024). "Meanwhile, medium- and high-renin hypertension responds well to other antihypertensive medications, like angiotensin-converting enzyme inhibitors, angiotensin receptor blockers, and β-blockers, all of which antagonize plasma renin activity." (PMID 39184766, 2024).
Hypertension (continued). "We hypothesize that a large proportion of people with low-renin hypertension is mediated by excess mineralocorticoid receptor (MR) activation and that targeted treatment with an MR antagonist (MRA) will be beneficial." (PMID 39026100, 2024). "In addition, evidence suggests that AST can alleviate hypertension by modulating the renin–angiotensin system." (PMID 39852511, 2024). "Corn gluten meal protein hydrolysate was found to not only inhibit ACE and renin activity, but also to regulate the biosynthesis and metabolism of fatty acids, sex hormones, and aldosterone through a rat model of spontaneous hypertension, thus contributing to a reduction in hypertension." (PMID 39408244, 2024). "Other mechanisms pertinent to the preventive role of physical activity in high blood pressure involved the reduction in sympathetic nervous system activity, modulation of the renin–angiotensin–aldosterone system, and attenuation of systemic vascular resistance." (PMID 38398871, 2024). "ACE2 is prominently expressed in the heart and plays a crucial role in counterbalancing the effects of angiotensin II, especially in conditions marked by excessive activation of the renin-angiotensin system, such as hypertension (HTN), congestive heart failure (CHF), and atherosclerosis." (PMID 39119143, 2024). "According to previous publications patients with low-renin essential hypertension have an increased F/E ratio both in urine and serum samples compared with normotensive subjects, which is negatively associated with serum aldosterone and PRA, as occurs in AME syndrome." (PMID 38586159, 2024). "Comparative studies between ADPKD patients with hypertension and normal renal function and those with essential hypertension have shown higher levels of plasma aldosterone and renin in ADPKD subjects in orthostatic and clinostatic positions, and after ACE-inhibitor (Captopril) stimulation." (PMID 39200287, 2024). "CBLN1 is a novel appetite-stimulating peptide related to renin expression that may be mediated by hypothalamic neuropeptide, which is a sympathetic neurotransmitter related to hypertension and a variety of CVDs." (PMID 36984843, 2023). "Additionally, this buildup has the potential to activate the renin–angiotensin–aldosterone system (RAAS), which can result in hypertension and insulin resistance, both of which are known to be risk factors for kidney injury." (PMID 37691097, 2023). "Although the mechanism through which alcohol raises blood pressure remains unclear, stimulation of the renin–angiotensin–aldosterone system, increased cortisol levels, and increased vascular reactivity may contribute to hypertension." (PMID 37893857, 2023). "Moreover, 1,25(OH)2D is suggested as a negative regulator of the renin–angiotensin system, thus having a potential role in hypertension." (PMID 37510843, 2023). "The AGT/renin/ACE/Ang II/AT1R axis is responsible for the vasoconstrictive, proliferative, and inflammatory effects whilst its de-regulation is linked to cardiovascular pathology, renal disease and hypertension." (PMID 37308552, 2023). "Population-based studies have reported that renin activity of postmenopausal women is considerably up-regulated, and some gene polymorphisms of renin significantly associated with hypertension incidence in women aged 40–70 years, but not in men." (PMID 37528365, 2023). "Surprisingly, 1,25(OH)2D3 levels influences renin expression, resulting in hypertension." (PMID 36788562, 2023). "Activation of the renin-angiotensin system (RAS) is linked to AF, particularly in hypertension." (PMID 38203704, 2023). "The renin-angiotensin system, the proportion of intra-abdominal and intravascular fat, sodium retention that raises renal reabsorption, and the sympathetic nervous system are all thought to play essential roles in the etiology of obesity-related hypertension." (PMID 37198582, 2023).
Hypertension (continued). "It is reported that accumulation of fat in the renal sinus may promote hypertension due to compression of the lymphatic and venous vessels by perirenal fat, leading to activation of the renin-angiotensin-aldosterone system." (PMID 36959658, 2023). "Strikingly, the kidneys of heterozygous SMC-specific knockout mice expressing Cre recombinase under the control of mouse smooth muscle cell protein 22-α promoter (Prdm6fl/+ SM22-Cre) exhibited a markedly higher number of renin-producing cells and developed hypertension when fed a high-salt diet." (PMID 36602864, 2023). "In 5 out of 6 controls with low-renin hypertension, which might represent a PA spectrum, renin remained suppressed." (PMID 38075562, 2023). "In addition, vitamin D suppresses the expression of the renin gene and down-regulates the renin-angiotensin system (RAS) which is a major contributor to hypertension and cardiac remodelling." (PMID 36882686, 2023). "In particular, renin–angiotensin–aldosterone system (RAAS) is hyperactivated rapidly in the absence of clinically hypertension and the loss of renal function." (PMID 37043156, 2023). "The treatment of COVAN is typically supportive with interventions including dietary sodium restriction of 2.3 g/day, optimization of hyperlipidemia and hypertension, blockade of the renin-angiotensin-aldosterone system, sodium/glucose cotransporter-2 inhibition, and maintenance of euvolemia." (PMID 37485073, 2023). "This could enhance renin production by acting upon juxtaglomerular cells, hence implying that inflammation is a major factor regarding renin-driven hypertension." (PMID 38161941, 2023). "Purinergic signalling plays a crucial role in hypertension through the sympathetic nerve system, neurons in the brain stem, carotid body, endothelium, immune system, renin-angiotensin system, sodium excretion, epithelial sodium channel activity (ENaC), and renal autoregulation." (PMID 35181831, 2023). "Several mechanisms may be responsible for nocturnal hypertension: increased sympathetic nervous system activity, hyperactivity of renin-angiotensin-aldosterone system, sodium retention, renal function impairment, etc.." (PMID 37189519, 2023). "We analyzed left ventricular samples from 1-year-old female and male transgenic (TG) rats homozygous for the rat Ren-2 renin gene (mRen2) characterized with hypertension and diastolic dysfunction and compared it to age-matched female and male wild type rats (WT) served as control." (PMID 37363100, 2023). "A previous review in 2017 by Dr. Burnstock showed alteration of purinergic signalling contributes to hypertension in 6 different ways, including sympathetic nerve activities, endothelial cells, neurons in the brain stem, carotid body, inflammation, and renin-angiotensin system." (PMID 35181831, 2023). "Renin-angiotensin system inhibitors (RASi), particularly angiotensin-converting enzyme inhibitors (ACEIs) and angiotensin II receptor blockers (ARBs), are commonly used in the treatment of hypertension and are recommended for kidney protection." (PMID 38040765, 2023). "The synergistic effects of excess ROS production, DOX, and hypertension on the renin-angiotensin system (RAS) may be an important potential mechanism." (PMID 36742068, 2023). "In patients with obesity, adipocyte hypertrophy (in response to increased caloric intake) and adipokine dysregulation lead to sodium retention, activation of the renin-angiotensin-aldosterone system, hypertension, insulin resistance, and increased inflammation." (PMID 37629724, 2023). "In CHF and many forms of hypertension, the renin-angiotensin system is hyperactivated." (PMID 37719456, 2023). "A common preclinical model of hypertension characterized by low circulating renin is the “deoxycorticosterone acetate (DOCA)-salt” model, which influences blood pressure and metabolism through mechanisms involving the angiotensin II type 1 receptor (AT1R) in the brain." (PMID 37293629, 2023).
Hypertension (continued). "Interestingly, the authors of this study noted that spironolactone monotherapy, when used to treat hypertension in these low-renin premature neonates, achieved greater success compared to other antihypertensive agents." (PMID 36409371, 2023). "Similarly, a new onset of hypertension in the post-partum period led to PA diagnosis in several patients, who showed high BP values and hypokalemia with suppressed renin and high aldosterone levels, mostly due to unilateral forms of PA." (PMID 35536535, 2023). "In addition, some preterm neonates with hypertension were found to have elevated plasma renin activity (PRA) and serum aldosterone (SA) levels, whereas other studies reported low renin being associated with hypertension." (PMID 36409371, 2023). "The HPA axis activates cortisol secretion and the renin–angiotensin system, resulting in problems such as hyperglycemia, inflammation, and hypertension, while the SNS stimulates the secretion of the neurotransmitters epinephrine and norepinephrine, worsening HRV and blood viscosity." (PMID 37893842, 2023). "Renin, a hormone secreted by the kidneys, acts on its substrate to catalyze the transformation of angiotensinogen into angiotensin I. Angiotensin I is known to be a powerful vasoconstrictor that contributes to the development of hypertension." (PMID 37869088, 2023). "Ren-2 renin transgenic rats (TGR) were used as a model of hypertension." (PMID 36204993, 2023). "GSNO-loaded nanoparticles reduced CKD-induced hypertension, which was related to an enhanced endogenous NO-generating system, reduced renal oxidative stress, and downregulated several components belonging to the classic renin–angiotensin (RAS) system." (PMID 36830071, 2023). "Additionally, SHR is a normal-to-low renin and normal-to-low angiotensin/aldosterone model of hypertension, whereas the sympathetic nervous system seems to be a dominant player in the development of hemodynamic, structural, and functional alterations in SHR." (PMID 37875978, 2023). "Insulin resistance sensitizes the vascular smooth muscle cells through high levels of insulin, interferes with the control of blood pressure by the renin-angiotensin-aldosterone system, increases the resistance of vascular smooth muscle, and leads to hypertension and myocardial remodeling." (PMID 37900136, 2023). "The high prevalence of hypertension in the present study (80%) might reflect the activation of the renin-angiotensin system or the sympathetic nervous system in ADPKD patients." (PMID 36833371, 2023). "Therefore, exogenous H2S attenuates renin release and promotes renin-vesicular autophagy to relieve diabetes-induced hypertension." (PMID 36675205, 2023). "Moreover, the aberrant renin-angiotensin system (RAS) and deficiency in nitric oxide (NO) also anticipate hypertension programming in various animal models, such as the maternal high-fructose diet model." (PMID 37049522, 2023). "Nevertheless, TRα is also related to renin–angiotensin system expression, and one or more thyroid-regulated transcripts in the circulation may indicate a thyroid-hypertension relationship." (PMID 38069004, 2023). "Direct-acting vasodilators were used in the treatment of hypertension by directly relaxing vascular smooth muscle but may have destructive effects on the aortic wall by activating the renin–angiotensin system axis." (PMID 37383707, 2023). "Notably, in patients affected by arterial hypertension, renin activity was found to be inversely related to 1,25(OH)D levels." (PMID 37761831, 2023). "The reasons for this trend are not clear; however, it is hypothesized that the wider prescription of renin-angiotensin inhibitors in clinical practice and the better pharmacologic control of hypertension and dyslipidemia may have contributed to it." (PMID 37241201, 2023). "The renin–angiotensin–aldosterone system is positively correlated with T2D and hypertension." (PMID 37569338, 2023).
Hypertension (continued). "However, the principal side effects of the CBX are sodium retention, hypokalemic alkalosis, suppressed plasma renin, and hypertension." (PMID 37232747, 2023). "Further work is required to distinguish whether eGCSS is a more direct measure of cellular sensitivity to the damage induced by sodium than renin and if its correlation to hypertension mediated target organ damage is superior to that of renin." (PMID 35414109, 2023). "Furthermore, thyroid hormone has a connection with critical points of hypertension pathogenesis: the vascular smooth muscle, renal perfusion, renin-angiotensinogen-aldosterone system, autonomic nervous system, and myocardial contractibility." (PMID 38069004, 2023). "Regarding the participation of RAAS in ethanol-induced hypertension, pioneering works by many researchers revealed increases in the circulating levels of renin and aldosterone in heavy drinkers and experimental studies strengthened the proposal that ethanol consumption activates RAAS." (PMID 37891892, 2023). "In contrast, T1DM mediated hypertension is accompanied with hyperfiltration followed by an increase in renin production which hypothetically could depress the tubular EGF production." (PMID 36996194, 2023). "Elucidating the regulatory mechanism of renin expression in JGC may contribute to the treatment of hypertension, a condition in which the normal function of the myogenic response and TGF system is lost." (PMID 36831037, 2023). "The Ren2 rat, by overexpressing mouse (pro)renin, displays angiotensin II‐dependent hypertension." (PMID 36106615, 2023). "Lavie and his colleagues have stated several factors for the paradox between obesity and CVDs, such as the presence of protective cytokines in obese individuals, poor response to the renin–angiotensin–aldosterone system, and hypertension in these individuals, which leads to the use of cardiac drugs." (PMID 37308989, 2023). "Low-renin phenotype has been previously characterized in hypertension." (PMID 38075562, 2023). "The fact that cAMP is one of the main stimulating factors for renin production in renal juxtaglomerular cells makes it easy to understand how vitamin D might play a potential role in hampering the development of arterial hypertension." (PMID 37761831, 2023). "Renin is normally suppressed in WT mice on a high-salt diet or with essential hypertension." (PMID 36602864, 2023). "The theoretical mechanisms with relation to obesity and high blood pressure include renin-angiotensin-aldosterone system stimulation, alteration of the functional and structural kidney, changes in adipose-derived cytokines, and sympathetic nervous system overaction." (PMID 36833764, 2023). "Nevertheless, systematic reviews of the literature show that pregnant women with PA usually maintain lower plasma renin activity (PRA) levels compared to either normotensive individuals or pregnant subjects with essential hypertension, being suppressed in approximately 60% of the described cases." (PMID 35536535, 2023). "The enhancement of the renin–angiotensin signaling pathway may also induce hypertension less responsive to treatment in patients with psoriasis." (PMID 36012327, 2022). "Our previous work revealed that dimethyl fumarate administration during pregnancy protected adult offspring from the hypertension programmed by prenatal dexamethasone plus a postnatal high-fat diet (which are relevant to the downregulated mRNA expression of renin, angiotensinogen, ACE, and AT1R)." (PMID 35955421, 2022). "Insulin resistance may play a role in the pathogenesis of hypertension, potentially via adverse effects on the renin-angiotensin system, sympathetic nervous system, and renal sodium retention." (PMID 35436969, 2022).